MAGEL2 (MAGE family member L2)
Diseases named in the same sentence as MAGEL2 in open-access papers (continued):
Sharing a sentence is not in itself a finding about the gene and the disease.
Schaaf-Yang syndrome (continued). "We consider that as Schaaf-Yang syndrome is a neurodevelopmental disorder, and MAGEL2 plays an important role in the fetal brain, thereby limiting fetal movement." (PMID 29581464, 2018). "Altered mRNAs include MAGEL2, causal in the PWS-like disorder Schaaf-Yang syndrome." (PMID 39616178, 2024). "PWS is also characterized by thermosensory abnormalities as well as Schaaf-Yang syndrome (SYS), which has several overlapping features with PWS but is caused by pathogenic/truncating variants of the melanoma antigen L2 gene (MAGEL2), and a diagnosis of ASD is more frequent." (PMID 38396741, 2024). "Moreover, individuals carrying a mutation of MAGEL2 have been identified in a cohort of patients with ASD, and a new syndrome has subsequently been classified as Schaaf-Yang syndrome." (PMID 38396741, 2024). "However, the main aim of this study was to investigate the effect of early postnatal OXT treatment in male and female Magel2-KO mice in order to advance the translational research on OXT treatment for Schaaf-Yang Syndrome and Prader-Willi patients." (PMID 36998737, 2023). "In humans, the specific lack of expression of the MAGEL2 gene, causes a Prader Willi-like disease identified as Schaaf-Yang Syndrome (SYS; OMIM 615547)." (PMID 36998737, 2023). "In the Magel2-knockout (KO) mouse, a model of Schaaf-Yang Syndrome, an early postnatal administration of OXT rescued autistic-like behavior and cognition at adulthood, making this model relevant for understanding the actions of OXT in (re)programming postnatal brain development." (PMID 36998737, 2023). "We highly suggest that the MAGEL2 gene should be added to gene-panels or gene-filters in next-generation sequencing-based diagnostics, which is of great significance for early diagnosis and early intervention of Schaaf-Yang syndrome patients." (PMID 32702813, 2020). "In addition to SYS, truncating mutations of MAGEL2 cause arthrogryposis multiplex congenita (OMIM #208100) and Chitayat-Hall syndrome (OMIM #208080) that both display global developmental delay and growth hormone deficiency, similar to PWS and SYS." (PMID 32879135, 2020). "Paradoxically, while truncating mutations in the MAGEL2 gene cause Schaaf-Yang syndrome, MAGEL2 whole gene deletions cause on slight or even absent expression of the clinical phenotype." (PMID 30968677, 2020). "In addition, a small number of participants (n = 2) in the Global PWS Registry have a diagnosis of Schaaf-Yang syndrome, a PWS-related disorder caused by truncating mutations in the MAGEL2 gene, which resides in the PWS-region of chromosome 15." (PMID 31540108, 2019). "Moreover, deletion or mutation of USP7 has been shown to result in a neurodevelopmental disorder with overlapping symptoms to Schaaf-Yang syndrome (OMIM #615547), caused by mutations of MAGEL2." (PMID 29441128, 2018). "Schaaf-Yang syndrome (SYS) was originally considered Prader-Willi-like syndrome because it is caused by a nonsense frame shift mutation in the maternally imprinted and paternally expressed MAGEL2 gene located in the Prader-Willi critical region 15q11–15q13, also called the MAGEL2 loss of function." (PMID 38396741, 2024). "MAGEL2 is an autism susceptibility gene whose deficiency has been associated with autism-related behaviors in animal models and in syndromic human autism spectrum disorders (ASDs) such as Schaaf-Yang syndrome, but has not been studied in the broader autism spectrum." (PMID 39609859, 2024).
Obesity (23 papers, 2013 to 2026). Accumulation of substantial excess body fat. "Those genes were associated with severe obesity and Prader-Willi-like syndrome (SIM1), susceptibility to T2D (C2CD4B), and susceptibility to obesity with abdominal fat deposition (MAGEL2)." (PMID 40981068, 2025). "Loss of Magel2 in mice leads to neonatal growth retardation, obesity, altered circadian rhythm, and reduced motor activity." (PMID 37685915, 2023). "We reported a patient with MAGEL2 gene new site mutation who had mild intellectual disability, social fear, small hands and feet, obesity issues, dyskinesia, growth retardation, language lag and sexual development disorder." (PMID 34128869, 2021). "Magel2 mutation is associated with a postnatal failure to thrive, with pups that reach weaning age developing obesity and hyperinsulinaemia, with associated reduced energy expenditure, even in the face of hypophagia and hypoactivity." (PMID 31270580, 2019). "This retention of leptin-mediated inhibitory responses is consistent with the modest level of obesity in Magel2-null mice compared with leptin-deficient Lepob or leptin receptor null Leprdb mice." (PMID 23341784, 2013). "This neural defect leads to less repression of food intake and uncontrolled leptin-regulated fat storage; thus, the dysregulation of leptin receptor activity upon loss of Magel2 may be the underlying cellular mechanism for obesity in PWS." (PMID 37685915, 2023). "DNA methylation change of 15 imprinted genes induced by HFD feeding was observed, including Magel2, Ctnna3, Gab1, and L3mbtl1, that are reported to be linked to the pathogenesis of obesity, high cognitive processes in adulthood, circadian machinery, and growth and development of embryos." (PMID 35458198, 2022). "Hence, our study provides evidence that knockdown of the Magel2 gene in ARCPOMC neurons innervating the MeA reduces susceptibility to diet-induced obesity with increased locomotor activity through activation of central GPER." (PMID 36007929, 2022). "This neural defect, together with increased fat mass, blunted circadian rhythm, and growth hormone response pathway defects that are also linked to loss of MAGEL2, could contribute to the hyperphagia and obesity that are hallmarks of this disorder." (PMID 23341784, 2013). "We studied the impact of Clic1 inhibition in mouse models of binge-eating, diet-induced obese mice and genetic models of obesity (Magel2 KO mice)." (PMID 37604246, 2023). "Obesity also results from deletion of paternally expressed genes Peg3, Dlk1 or Magel2, with differences in feeding and energy expenditure, all of which exhibit early postnatal catch up growth in the null allele of each gene." (PMID 31270580, 2019). "Patients with MAGEL2 variants shared several features with PWS, such as neonatal hypotonia, poor suck, and obesity; however, there were also unique features, including arthrogryposis and a failure to acquire meaningful words." (PMID 31791363, 2019). "Obesity also results from deletion of paternally expressed genes, Peg3, Pref1/Dlk1, or Magel2 with observed differences in hyperphagia and energy expenditure, all of which demonstrate catch up growth in null mice." (PMID 30279096, 2018). "Taken together, these findings suggest that blocking CB1R at the periphery reverses obesity, reduces hyperphagia, and improves metabolic outcomes in obese Magel2-null mice." (PMID 27900261, 2016). "In addition, aged Magel2-KO mice developed adult-onset obesity and exhibited elevated HbA1c levels consistent with impaired glycemic control." (PMID 42275194, 2026). "It is worth noting that people with truncating MAGEL2 variants do not display the hallmark PWS hyperphagia-induced obesity." (PMID 36637363, 2023). "Neonatal Magel2 null mice fail to thrive, have a modest increase in embryonic mortality, and demonstrate growth retardation in early life, which is followed by weight gain after weaning, and increased obesity with disturbed metabolic and endocrine homeostasis." (PMID 36836222, 2023).
Obesity (continued). "Further, Necdin and Magel2 together were shown to control leptin receptor sorting and degradation through a ubiquitin-dependent pathway, including E3 ubiquitin ligase Rnf41, deubiquitinase Usp8, and protein Stam1, contributing to obesity in PWS." (PMID 37685915, 2023). "Therefore, we decided to test the efficacy of the peripherally restricted CB1R antagonist, JD5037, in treating obesity in Magel2-null mice." (PMID 27900261, 2016). "Dysregulation of the eCB/CB1R system may contribute to hyperphagia and obesity in Magel2-null mice and in individuals with PWS." (PMID 27900261, 2016). "As obesity and infertility are common in animal models with impaired leptin responses, we hypothesized that Magel2-null mice may also respond abnormally to leptin." (PMID 23341784, 2013). "Kanber and colleagues described a patient with deletions in MKRN3, MAGEL2, and NDN, exhibiting only obesity, developmental delay, and a high pain threshold as the primary clinical criteria for PWS." (PMID 38737552, 2024). "To explore the broader potential of Clic1 inhibition in genetic models of obesity, we tested the effect of IAA94 in the Magel2 KO mouse model of Prader–Willi syndrome." (PMID 37604246, 2023). "When administered a high-fat diet, Magel2 null mice display several features of PWS, including elevated appetite and obesity." (PMID 32326226, 2020). "We demonstrate that a novel, peripherally restricted CB1R antagonist, JD5037, is effective in reversing obesity and its deleterious metabolic effects in DIO Magel2-null mice, which exhibit fundamental aspects of the PWS phenotype." (PMID 27900261, 2016). "First, disruption of Magel2 in rats leads to alterations in body composition, highlighted by reduced body weight, whereas gross obesity was never observed." (PMID 36637363, 2023). "Magel2-null mice recapitulate many PWS features, like poor sucking and obesity." (PMID 37685915, 2023). "PWS animal models, such as Magel2- and Snord116-null mice fed with a standard chow diet did not develop the delayed-onset obesity described in PWS." (PMID 36007929, 2022). "And above all distinct symptoms, SYS does not usually cause the high appetite and severe obesity observed in PWS, which can disassociate MAGEL2 and the hyperphagia condition." (PMID 31920975, 2019). "We studied eCB ‘tone’ in individuals with PWS and in the Magel2-null mouse model that recapitulates the major metabolic phenotypes of PWS and determined the efficacy of a peripherally restricted CB1R antagonist, JD5037 in treating obesity in these mice." (PMID 27900261, 2016). "Moreover, specifically targeting the peripheral eCB system in obese Magel2-null mice was found to be as efficacious as in DIO animals, and, therefore, it may represent a novel approach to treating obesity and its complications in PWS." (PMID 27900261, 2016). "Hence, these prior studies suggest that the Magel2 gene, among the imprinted genes associated with PWS, might not be crucial in the development of hyperphagia and obesity." (PMID 41321745, 2025). "Patient 1 was deleted for MKRN3, MAGEL2, and NDN with no PWS major clinical criteria, except for obesity, developmental delay, and high pain threshold." (PMID 31920975, 2019).
autism (19 papers, 2015 to 2025). Persistent deficits in social interaction and communication and interaction as well as a markedly restricted repertoire of activity and interest as well as repetitive patterns of behavior. "In the SFARI autism database, the following DE genes were registered: Celf6, which codes for a transcription associated protein and was common to CvN and CvI; Magel2 (melanoma antigen family L2), unique to CvI; and Ampd1 (adenosine monophosphate deaminase), also unique to CvI." (PMID 27782041, 2016). "On this line it has been reported that when oxy is administered daily in the first postnatal week can prevent deficits in social behavior and learning abilities in mice deficient for the melanoma antigen family L2 (Magel2), a gene which has been found mutated in patients with autism." (PMID 26793046, 2015). "Aberrations in OXTR expression within the hippocampus have been documented in the Magel2 mouse model of autism." (PMID 39277552, 2025). "In conclusion, this pilot study of the MAGEL2 gene used the long-read nanopore sequencing method nCATS in adults with high-functioning autism within a case-control cohort." (PMID 39609859, 2024). "Individuals with truncating mutations on the paternal allele of MAGEL2, a gene within the PWS domain, were recently found to exhibit both features of PWS and autism." (PMID 28264487, 2017). "Could it be that the subtleties of the known sex differences in autism are also influenced by epigenetic regulatory differences in MAGEL2?" (PMID 39609859, 2024). "Given the capabilities of long-read sequencing technologies, this pilot study used a targeted nanopore sequencing approach to simultaneously examine MAGEL2 DNA sequence and methylation in adults with high-functioning autism (HFA) compared to neurotypical controls (NC)." (PMID 39609859, 2024). "Here we found that under cool environment neonatal mice lacking the autism-associated gene Magel2 present pup calls hypo-reactivity and are retrieved with delay by their wild-type dam." (PMID 35396500, 2022). "Moreover, even PWS and AS specific genes that lie in the BP2-BP3 PWS/AS region, such as, MAGEL2, SNRPN, UBE3A, and ATP10A are also significantly co-associated with autism (Malacards.org; SFARI.org)." (PMID 32384786, 2020). "In addition, autism-like behaviors can be observed in MAGEL2 knockout (KO) mouse models." (PMID 39609859, 2024). "Furthermore, to our knowledge, MAGEL2 alterations and their association with autistic symptoms have not been investigated in human autism case-control samples." (PMID 39609859, 2024). "Because Oxtr and Magel2 are co-expressed in aCA2/CA3d hippocampus in infancy (P7), and because in Oxtr KO mice, as in several models of autism, the depolarizing to hyperpolarizing developmental GABA shift is delayed, we investigated the GABA-shift timing in Magel2-KO pups." (PMID 34290367, 2021). "The lack of joint contractures, autism characteristics, and hyperphagia suggest that complete deletion of the paternal copy of the MAGEL2 gene and promoter could lead to leaky expression of the maternal copy of MAGEL2, as observed in mice." (PMID 37685915, 2023).
autism spectrum disorder (10 papers, 2016 to 2024). A spectrum of developmental disorders that includes autism, and Asperger syndrome. "Furthermore, patients with truncating variants in MAGEL2 have a higher prevalence (67%) of autism spectrum disorder (ASD) than patients with classical PWS." (PMID 36836222, 2023). "Given that frameshift mutations in MAGEL2 cause autism spectrum disorder, our study raises the possibility that an untapped reservoir of mutations in the intrinsically disordered N-terminus of MAGEL2 could contribute to some of the missing heritability in neurodevelopmental disorders." (PMID 34265304, 2021). "However, patients with a heterozygous truncating pathogenic variant in the paternally derived allele of the MAGEL2 gene have Schaaf–Yang syndrome, which has clinical overlap with PWS, including intellectual disability, autism spectrum disorder, neonatal hypotonia, and infantile feeding problems." (PMID 34200226, 2021). "Autism spectrum disorder (ASD) -common in MAGEL2-mutated patients- could not be evaluated due to her severe intellectual disability." (PMID 28281571, 2017).
developmental delay (8 papers, 2017 to 2024). "She presented with developmental delay, which is observed among all surviving patients with MAGEL2 mutations, neonatal hypotonia, feeding problems in infancy and arthrogryposis or joint contractures, all traits common to the majority of the patients with MAGEL2 mutations." (PMID 28281571, 2017). "Therein, specific point mutations on the paternal allele of MAGEL2 were reported in 4 individuals with PWS spectrum phenotype: muscle hypotonia, weight gain, developmental delay, and hypogonadism." (PMID 31920975, 2019).
Intellectual disability (8 papers, 2017 to 2023). "Magel2 is one of the affected genes located on 15q11-q13, and Magel2 mutations have been found in individuals with ASD, intellectual disability and PWS." (PMID 37367062, 2023).
Angelman syndrome (5 papers, 2019 to 2025). A neurogenetic disorder characterized by severe intellectual deficit and distinct facial dysmorphic features. "Moreover, a cluster of genes in the BTA21 (GABRG3, MAGEL2, MKRN3, NDN, SNRPN, and SNURF) was significantly associated (FDR = 1.07 × 10−6) with the Prader-Willi and Angelman syndromes pathway in the PPI analysis." (PMID 35692843, 2022). "MKRN3, MAGEL2 and NDN are three maternally imprinted genes in the human Prader-Willi and Angelman syndromes imprinted locus at 15q11-q13." (PMID 34359112, 2021).